RTL10 (retrotransposon Gag like 10)
Description:
Could induce apoptosis in a BH3 domain-dependent manner. The direct interaction network of Bcl-2 family members may play a key role in modulation RTL10/BOP intrinsic apoptotic signaling activity.
Synonyms: BOP; C22orf29; FLJ21125
Tractability: PROTAC: ubiquitination databases record sites on it.
Gene: Protein-coding gene on chromosome 22 (19,846,138 to 19,854,896, reverse strand). Ensembl gene ENSG00000215012.
Subcellular location: Mitochondrion
Gene Ontology:
Molecular function: protein binding
Biological process: mitochondrial outer membrane permeabilization; regulation of mitochondrial membrane potential
Cellular component: mitochondrion
Genetic constraint (gnomAD): Missense variants: 477 observed, 490.96 expected, observed/expected ratio (o/e) 0.97, 90% interval 0.9 to 1.05. Synonymous variants: 199 observed, 196.38 expected, observed/expected ratio (o/e) 1.01, 90% interval 0.9 to 1.14.
Homologues: Orthologues: rabbit RTL10 (69% identical), macaque GNB1L (63% identical). Paralogues in human: RTL3 (15% identical), RTL6 (15% identical), RTL5 (15% identical), PEG10 (14% identical), RTL1 (12% identical), RTL8C (9% identical), RTL8A (9% identical), LDOC1 (9% identical), RTL8B (9% identical), RTL4 (6% identical).
Diseases named in the same sentence as RTL10 in open-access papers:
RTL10 is named in the same sentence as 18 diseases in open-access papers, as found by Europe PMC text mining. Sharing a sentence is not in itself a finding about the gene and the disease.
RTL10 shares sentences with these, for which no sentence is quoted: cancer (9 papers); melanoma (4); breast carcinoma (3); infection (2); leukemia (2); multiple myeloma (2); tumor (2); bacterial sepsis (1); cardiovascular disease (1); colon carcinoma (1); colorectal cancer (1); glioma (1); Obesity (1); osteosarcoma (1); pancreatic ductal adenocarcinoma (1); prostate carcinoma (1); renal carcinoma (1); status epilepticus (1).